Y_RNA (Y RNA )
Gene: Miscellaneous RNA gene on chromosome 5 (149,940,030 to 149,940,131, reverse strand). Ensembl gene ENSG00000200334.
Homologues: Orthologues: chimpanzee Y_RNA (99% identical), pig Y_RNA (73% identical). Paralogues in human: Y_RNA (88% identical), Y_RNA (86% identical), RNY3 (85% identical), Y_RNA (85% identical), RNY3P2 (84% identical), Y_RNA (84% identical), Y_RNA (83% identical), RNY3P1 (82% identical), Y_RNA (82% identical), Y_RNA (81% identical), RNY3P16 (80% identical), RNY3P4 (80% identical), and 95 more.